CDK7 (cyclin dependent kinase 7)
Diseases named in the same sentence as CDK7 in open-access papers (continued):
Sharing a sentence is not in itself a finding about the gene and the disease.
tumor (continued). "Therefore, CDK7 inhibition restores sensitivity of HER2iR tumor cells to the effects of HER2 inhibitors through decreased cell proliferation and increased induction of apoptotic cell death." (PMID 31462705, 2020). "Based on the hypersensitivity of HER2+ BC cells to THZ1, we next investigated whether HER2 expression affects CDK7 activity tumor cells." (PMID 31462705, 2020). "Specifically, we tested whether inhibition of CDK7 restored the sensitivity of three HERiR tumor cell lines HCC1569, HCC1954, and MDAMB453, which are intrinsically resistant to HER2 blockade." (PMID 31462705, 2020). "Given the possible role of CDK7 in oncogenesis, stemness, and tumor growth, we next examined whether inhibition of CDK7 by siRNA or THZ1 affected tumor cell growth by using a sulforhodamine B (SRB) assay." (PMID 32340192, 2020). "As clinical trials progress, analyses of tumour features enriched in subsets of patients that are intrinsically resistant to CDK7 inhibitors, or those who acquire resistance after initially responding well, should help shed light on mechanisms of CDK7 inhibitor resistance." (PMID 32385714, 2020). "Therefore, we evaluated the functional importance of the regulation of PD-L1 expression by CDK7 in tumor progression and tested the combination of therapeutic blockade of CDK7 and PD-1 in vivo." (PMID 32690037, 2020). "Dual HER2 and CDK7 inhibition induced tumor regression in two HER2iR BC xenograft models in vivo." (PMID 31462705, 2020). "We show that Milciclib decreases H460 cell xenograft 18F-FDG consumption, possibly suggesting that decreased tumor 18F-FDG consumption measured by PET in patients could be used as a pharmacodynamic biomarker of CDK7 inhibitors." (PMID 31784510, 2019). "Moreover, CDK7 mRNA expression was significantly higher in CCA than normal bile ducts or surrounding non-tumor liver tissues in GEO GSE26566 dataset, GSE107943 dataset, GSE32225 dataset, GSE76297 dataset, and GSE32879 dataset." (PMID 31399555, 2019). "We guessed that VEGF and CDK7 may reciprocally increase their expression of each other for amplifying the angiogenic response during tumor progression." (PMID 31752390, 2019). "While there is substantial evidence supporting a reciprocal regulatory relationship between lncRNAs and CDK7 in various tumor types, a significant gap persists: no direct evidence has yet been established linking lncRNAs associated with BC metastasis to the regulation of CDK7." (PMID 40223929, 2025). "However, the interaction between CDK7 and the unique YSPTSPA heptapeptide repeats in Phytophthora RNPII is unclear, the exploration of CDK7 repressor could further the development of new anti-tumor drugs." (PMID 38640110, 2024). "However, we found significantly higher CDK7 expression in immune-infiltrated tumor tissue." (PMID 35158760, 2022). "Moreover, CDK7 was positively correlated with E-cadherin, tumor grade, and tumor metastasis." (PMID 34741018, 2021). "Interestingly, both p38α and MYC are reported to be linked with the remodeling of tumor immune microenvironment, suggesting that CDK7/p38α/MYC pathway may play a prominent role in the tumor immune microenvironment of NSCLC." (PMID 32690037, 2020). "Thus, we speculated that CDK7 ablation could prevent the immune escape of tumor cells by suppressing the MYC/PD-L1 axis." (PMID 32690037, 2020). "Moreover, high CDK7 expression, high MYC expression, and low tumor-infiltrating lymphocytes (TILs) could serve as three risk factors to differentiate NSCLC patients with different survival outcomes." (PMID 32690037, 2020). "However, the mechanisms involved in CDK7-mediated tumor immune evasion are unclear in NSCLC." (PMID 32690037, 2020). "Next, we investigated whether CDK7 inhibition could suppress tumor growth in vivo." (PMID 32174795, 2020). "Individual constituents of super enhancers, such as BRD4, CDK7, or CDK9, have demonstrated significant potential in multiple preclinical tumor models." (PMID 39838405, 2025).
tumor (continued). "GRP78 also plays a significant role in promoting tumor growth and metastasis, including through interactions with CRIPTO or CDK7." (PMID 40223122, 2025). "Cyclin-dependent kinase 7 (CDK7) has been recently identified as a promising target in multiple human and mouse PDAC preclinical tumor models, due to significant downregulation of gene transcription and preferential inhibition of the mitotic cell cycle." (PMID 40853714, 2025). "Another CDK7 inhibitor, THZ1, has been validated in several preclinical in vitro and in vivo tumour models." (PMID 40163908, 2025). "In vivo, it inhibits PKCι/ζ, downregulates the phosphorylation of CDK7 and CDK2, blocks the cell cycle at the G0/G1 phase, and induces PARP cleavage (an apoptotic marker), thereby reducing tumor cell proliferation." (PMID 41244006, 2025). "In NSCLC cells, the CDK7 inhibitor THZ1 inhibits MYC transcriptional activity by downregulating p38α, thereby suppressing PD-L1 expression and improving the anti-tumor immunity against PD-1 therapy in vivo by recruiting infiltrating CD8+ T cells." (PMID 38762484, 2024). "For instance, the transcription factor TFIIH is important in transcription and DNA repair, its CDK7 subunit can regulate the transcription of PD-L1 in a MYC-dependent manner and promote tumor progression." (PMID 38762484, 2024). "Accordingly, CDK7 knockdown in SJSA-1 cells reduced phosphorylation of the RNAPII CTD and reduced tumor volume and weight in xenograft models compared with tumors derived from wild-type cells." (PMID 36839989, 2023). "In this tumor type, CDK6 and FGFR2 were less expressed than in normal tissue, whereas CDK7, MET, ALK and AURKB stood out as upregulated in tumor samples." (PMID 36839989, 2023). "For example, the BRD4 inhibitor JQ1 can induce neuron-like differentiation and delay tumor growth in a mouse model of DIPG, and the CDK7 inhibitor THZ1 can disrupt transcription and inhibit DIPG growth." (PMID 36720920, 2023). "CDK7 was significantly overexpressed (log2FC = 2.92, p < 0.05, and FDR < 0.25) in NSCLC tumor B cells vs. normal B cells." (PMID 35804895, 2022). "Pre-treatment of tumour-bearing mice with THZ1, a CDK7/CDK12/13 inhibitor, before infusion with CAR T-cells attenuated cytokine release by suppressing transcription of inflammatory genes, thus preventing the associated systemic toxicity." (PMID 35568739, 2022). "The overexpression of PSMB6, HSPA9, DUT, CDK7, and PLK1 was seen in resected tumor tissues compared with adjacent normal tissues, while FOLR2 was expressed more in normal tissues." (PMID 34721732, 2021). "This includes targeting CDK7 in order to prevent RNAPII phosphorylation and subsequent transcription initiation, with the CDK7 inhibitor THZ1 having been shown to suppress tumour growth in orthotopic DMG orthotopic." (PMID 34944870, 2021). "The transcriptional element, for example, bromodomain-containing protein 4 (BRD4) and cyclin-dependent kinase 7 (CDK7), has been reportedly the treatment target due to tumor-specific SEs." (PMID 34722892, 2021). "Meanwhile, on the TCGA portal, we found that CDK7, CDK8, CDK9, CDK12, CDK19, and CDK20 mRNA levels were differentially expressed in the 4 molecular tumor subtypes." (PMID 33686962, 2021). "The more global acting CDK7/12/13i THZ1 induced apoptosis, inhibited tumor growth, and prevented resistance in murine xenograft models." (PMID 33161487, 2021). "Seliciclib, a first generation aminopurine inhibitor of CDK2, CDK7 and CDK9, has shown anti-proliferative activity in tumor cell lines and xenografts." (PMID 32645016, 2020). "The cyclin-dependent kinase 7 (CDK7) subunit of TFIIH regulates RNA polymerase-II-based transcription and promotes tumor progression." (PMID 32690037, 2020). "Because CDK7 is necessary for the expression of MYC, which is important for vasculogenesis and angiogenesis throughout tumor development and progression, we also studied the effects of CDK7 inhibition on angiogenesis." (PMID 32340192, 2020).
tumor (continued). "Combined treatment with CDK7 and lapatinib greatly inhibited both HER2 activation and RNA Pol II phosphorylation and enhanced tumor cell apoptosis as assessed by increased levels of the active form of PARP." (PMID 31462705, 2020). "An extension of this work to other tumour types and in vivo studies would be required to further investigate the generality of ABC-transporters in CDK7 inhibitor resistance." (PMID 31530935, 2020). "Seliciclib is an ATP competitive inhibitor of CDK2, CDK7 and CDK9, with an average anti-proliferative activity (IC50) in tumor cells of around 15 μM." (PMID 32645016, 2020). "Recent studies showed that the combination of a bromodomain inhibitor with a CDK7 inhibitor, an AURKA inhibitor or an HDAC inhibitor is significantly more effective in suppressing MYCN-driven NB tumor growth than either drug alone." (PMID 33628735, 2020). "In this study, we demonstrated that inhibition of CDK7, a highly expressed transcriptional regulator in ICC, has therapeutic effects on ICC tumor growth and invasion." (PMID 32174795, 2020). "super-enhancers often drive the high-level expression of oncogenes, and super-enhancer inhibition by CDK7 and BET inhibitors can effectively block tumor cell proliferation and enhance survival in mouse models of disease (43, –, 45)." (PMID 30021904, 2018). "Unlike normal cells, tumor cells depend on CDK7, providing a rationale for investigating CDK7 inhibitors as chemotherapeutic agents." (PMID 41171060, 2025). "Similarly, quercetagitrin enhanced the inhibitory effects of defactinib and ponatinib on the expression of CDK7/9, Ki67, and LYVE1 in primary tumor tissues and the activation and expression of Yamanaka transcription factors in lymph nodes." (PMID 40887473, 2025). "Comparative analysis reveals elevated CDK7 expression in tumor tissues across a spectrum of neoplasms, including but not limited to breast." (PMID 38605321, 2024). "We therefore hypothesised that inhibiting CDK7, in combination with CDK4/6 inhibition with palbociclib, could target alternative pathways and prevent palbociclib-insensitive tumour growth." (PMID 37190140, 2023). "Cyclin-Dependent Kinase 7 (CDK7) is a CDK-activating kinase (CAK), and as a component of the general transcription factor TFIIH, it mediates RNA polymerase-II-based transcription and contributes to tumor progression." (PMID 37385987, 2023). "CDK7 staining was semi-quantified scored as 0 to 3+ using signal intensity in the tumor cell nuclei (no staining = 0, weak = 1, moderate = 2, strong = 3)." (PMID 36212402, 2022). "In summary, our findings indicate that targeting CDK7 with THZ1 may be a new plausible strategy to treat HCC, in which MYC plays crucial roles in cell proliferation and tumor growth." (PMID 35406486, 2022). "Our studies indicate that targeting gene transcription by CDK7 inhibition could be a new effective strategy against HCC, in which MYC plays crucial roles in tumor initiation and progression." (PMID 35406486, 2022). "Our findings indicate that targeting CDK7 with THZ1 may be a new plausible strategy for treating HCC, in which MYC plays crucial roles in cell proliferation and tumor growth." (PMID 35406486, 2022). "Besides, the level of CDK7 was higher in ESCC tissues with lymph node metastases compared to control group and positively correlated with tumor metastasis and patients’ overall survival." (PMID 36387198, 2022). "A number of studies have now indicated CDK7 and CDK9 play a role in maintaining genome stability, and inhibition of their activity may sensitise tumours to immune checkpoint inhibitors." (PMID 35568739, 2022). "CDK7 and CDK9 are key regulators of transcription initiation and elongation, respectively, supporting the concept of targeting transcriptional dependencies in tumor cells." (PMID 34215733, 2021). "CDK7 silencing and CDK7 inhibitor THZ1 elicited apoptosis and suppressed tumor growth." (PMID 32690037, 2020).
tumor (continued). "Additionally, a recent study has indicated that tumorigenesis can be effectively managed by targeting the CDK7-mediated CDK4/RB pathway and that FERM domain-containing 8 disrupts the interaction of CDK7 with CDK4, thereby inhibiting the activation of CDK4 to affect tumor growth." (PMID 40486867, 2025). "A more recent study found that CDK7 inhibition with samuraciclib increased expression of the immune checkpoint protein PD-L1 and increased infiltration of M1 macrophages and CD8+ cytotoxic T lymphocytes into TNBC tumours, which improved the efficacy of a PD-L1 inhibitor." (PMID 40163908, 2025). "However, continued tumour growth was evident when we combined palbociclib with the novel CDK7 inhibitor ICEC0942 (CDK7i) during the second cycle of treatment." (PMID 37190140, 2023). "In the H226 xenograft, tumor growth was suppressed by DCA/Nic and partially mediated by apoptosis (downregulation of Bcl-2 and XIAP), anti-proliferation (decrease in expression of PCNA and Akt), G2/M arrest (CDK7 downregulation) and suppressed migration (decline in expression β-catenin)." (PMID 36304150, 2022). "Moreover, selective inhibition of CDK7 has been shown to induce DNA replication stress and genomic instability causing cell cycle arrest without affecting global RNAPII phosphorylation in tumor cells." (PMID 36577800, 2022). "We did not observe significant differences in CDK7 expression by tumor site." (PMID 35158760, 2022). "Thus, cumulative pressure on the transcriptional machinery using BET inhibitors, CDK7 inhibition, and TPL may hold greater potential in global disruption of SE elements in tumor cells." (PMID 33168807, 2020). "Taken together, these data suggest that the tumor suppressive effects of ERβ in TNBC are in part mediated by inhibition of genes involved in cell cycle progression and provide further support for the development of CDK1 and CDK7 specific inhibitors for the treatment of TNBC." (PMID 29228549, 2017). "We tested the activity of THZ1, an irreversible CDK7 inhibitor, on patient-derived primary HGG cell lines and ex vivo HGG patient tissue slices, using proliferation assays, microarray analysis, high-resolution respirometry, cell cycle analysis and in vivo tumor orthografts." (PMID 28504693, 2017). "This is consistent with the cell cycle alterations, mostly G2 arrest, detected in CDK7-targeted cells and point to CDK7 inhibition as an effective strategy to block functionally the CDK7-CDK1 axis in HNSCC, observations that could probably be extrapolated to other tumor types." (PMID 41193441, 2025). "We therefore administered the CDK7 inhibitor ICEC0942 (CDK7i) in combination with palbociclib during the second cycle of treatment to establish if inhibition of an additional CDK could inhibit growth of tumours that were no longer responding to palbociclib." (PMID 37190140, 2023). "When a 7-day break was introduced after 28 days (mimicking the clinical schedule), tumour growth resumed and was not inhibited by a second cycle of palbociclib, either alone or when combined with the bone-targeted agent, zoledronic acid (Zol), or a CDK7 inhibitor." (PMID 37190140, 2023). "In primary tumor tissue, the string correlations among CCNH, XPA, and SLK are interesting: CCNH and its correlation with CDK7 and, last but not least, the correlation of CDK7 in strings with RAD51C and XPA." (PMID 37240218, 2023). "Specifically, a co-upregulation of CDK7 and DAG1 was observed in normal lung B cells, but not in the tumor B cells (p < 0.05, one-tailed z-tests)." (PMID 35804895, 2022). "However, neither PIK-75 nor the other CDK7/9 inhibitors were as cytotoxic as daunorubicin against the mouse MLL-AF9 AMLs, despite reducing MCL-1 protein levels in a dose-dependent manner, even in the Mcl-1tg/MLL-AF9 tumours." (PMID 30470795, 2019).
infection (4 papers, 2022 to 2025). The state of being infected such as from the introduction of a foreign agent such as serum, vaccine, antigenic substance or organism. "The expression level of CDK7 was significantly increased in male mice after infection but decreased significantly compared to female mice in response to infection in combination with exogenous SP-A2 (1A0) protein." (PMID 35844510, 2022). "Note that the level of GFP signal intensity, i.e., the infection efficiency, was comparable for all five treatment settings, so it is evident that this reduction in CDK7 intensity was not solely caused by the inhibition of viral replication." (PMID 35269635, 2022). "The overwhelming majority of changed miRNAs were downregulated after infection and infection plus SP-A2 (1A0) protein rescue, and these were predicted to target genes that play a role in cell cycle and growth and proliferation pathways, such as CCND1, CCND2, CDK7, CDKN2A, E2F1, E2F2, E2F3, and MYC." (PMID 35844510, 2022).
blood cancers (3 papers, 2017 to 2025). "Although the current clinical trials of CDK7 inhibitors are focused on solid tumours, these results highlight the potential for CDK7 inhibitors to combat blood cancers, particularly if combined with BH3-mimetics." (PMID 32385714, 2020).
hematologic malignancies (3 papers, 2020 to 2025). "CDK7 and CDK9 inhibitors exemplify this strategy and have demonstrated efficacy in hematological malignancies, showing potential for GBM therapy." (PMID 40565099, 2025).
digestive system tumors (1 paper, 2023). "Therefore, inhibition of CDK7 is a promising therapeutic strategy against digestive system tumors." (PMID 36923930, 2023). "Therefore, inhibition of CDK7 and CDK9 is a promising therapeutic strategy for digestive system tumors." (PMID 36923930, 2023).
neurological disorders (1 paper, 2022). "However, roscovitine can also inhibit Cdk1, Cdk2, Cdk7, and Cdk9, the low selectivity for Cdk5 reduces its potential as a drug candidate targeting neurological disorders." (PMID 36438186, 2022).
CDK7 also shares sentences with these, for which no sentence is quoted: adenocarcinoma (2 papers); head and neck cancer (2); nasopharyngeal carcinoma (2); thyroid cancer (2); acute myocardial infarction (1); acute promyelocytic leukemia (1); Alzheimer disease (1); Arthritis (1); autoimmune disease (1); B-cell acute lymphoblastic leukemia (1); bile duct cancer (1); bladder cancer (1); brain tumor (1); cervical cancer (1); cervical tumor (1); Cognitive impairment (1); colon adenocarcinoma (1); cyst (1); dementia (1); depression (1); diabetes (1); diffuse large B-cell lymphoma (1); fungal infections (1); hepatitis B (1); hepatitis C (1); Hyperglycemia (1); intrahepatic cholangiocarcinoma (1); kidney clear cell carcinoma (1); lobular breast carcinoma (1); low grade glioma (1).
A further 13 diseases each share a sentence with CDK7 in 1 paper.